ENSG00000238745
Synonyms: LOC124901196
Gene: Small nucleolar RNA gene on chromosome 5 (138,623,479 to 138,623,582, forward strand). Ensembl gene ENSG00000238745.
Gene Ontology:
Biological process: RNA processing
Cellular component: nucleolus
Homologues: Paralogues in human: SNORD13D (86% identical), SNORD13 (83% identical), SNORD13E (83% identical), SNORD13P3 (82% identical), SNORD13P1 (81% identical).